AHR (aryl hydrocarbon receptor)
Diseases named in the same sentence as AHR in open-access papers (continued):
Sharing a sentence is not in itself a finding about the gene and the disease.
neurodegenerative disease (16 papers, 2018 to 2025). A disorder of the central nervous system characterized by gradual and progressive loss of neural tissue and neurologic function. "Like HIF-1, the Aryl hydrocarbon receptor (AhR) is a transcription factor implicated in aging, neurodegenerative disease, and ECM regulation." (PMID 37108212, 2023). "The involvement of AHR in the modulation of inflammation also suggests its participation in the chronic low-grade inflammation (so-called “inflammaging”), which is associated with aging and neurodegenerative diseases." (PMID 32183254, 2020). "Recent studies have demonstrated that the metabolites generated by the gut microbiota, either through dietary components or microbial activity, can ameliorate the progression of neurodegenerative diseases such as AD by promoting the activation of AhR." (PMID 39940973, 2025). "Most indole derivatives, such as ILA, IAA, and I3C, are endogenous ligands of the aromatic hydrocarbon receptor (AHR), while AHR signaling pathway can regulate immune responses and help to treat neurodegenerative diseases and tumors." (PMID 40535013, 2025). "Despite a plethora of factors have been recognized as playing an important role in the onset of neurodegenerative diseases, AHR signaling is gaining attention due to the link with gut commensal trp derivatives and the control of CNS inflammation." (PMID 39175504, 2024). "As such, there is much interest in the involvement of AHR as an integrator of microbial signals at intestinal and central levels to unveil gut-brain axis perturbation in neurodegenerative diseases." (PMID 39175504, 2024). "Compelling evidence indicates that AhR signaling pathways, especially after activation by endogenous AhR ligands (tryptophan metabolites), are involved in neurodegenerative diseases." (PMID 34685709, 2021). "Though the AHR has been shown to be integral throughout the body, the remainder of this review will be devoted to its role in select neurodegenerative diseases and the potential of targeting it for therapeutic purposes." (PMID 32947781, 2020). "Herein, we summarize our current knowledge, of AHR-controlled cellular processes and their impact on regulating pathobiology of select ocular and neurodegenerative diseases." (PMID 32947781, 2020). "A different relationship has been reported between the AHR and another neurodegenerative disease, Alzheimer’s disease (AD)." (PMID 32947781, 2020). "Given the participation and pivotal role of AHR-mediated gene transcription in a variety of physiological and pathological processes, targeting AHR provides therapeutic approaches for treating a range of autoimmune, neoplastic, and neurodegenerative diseases." (PMID 31848275, 2019). "KYNA is also an agonist for the aryl hydrocarbon receptor, an attractive target in neurodegenerative diseases, and may therefore contribute to immune and inflammatory regulation." (PMID 39273374, 2024). "Kynurenine can signal onto the aryl hydrocarbon receptor (AHR) to elicit pleiotropic responses from several cell types including epithelial and immune cells, or can be further metabolized into bioactive molecules to influence neurodegenerative disease." (PMID 34149693, 2021). "Finally, implications for AhR signaling as a component of age-related diseases of the brain, and its potential as a therapeutic target in neurodegenerative disease, are discussed." (PMID 34685709, 2021). "In addition, further validation of the findings in larger clinical studies is needed to know the role of arylhydrocarbons and AHR in aging or neurodegenerative diseases." (PMID 32183254, 2020). "In the neurodegenerative diseases PD and HD, AhR may contribute to pathogenesis by altering the expression of ECM genes including MMPs, TIMPS, and genes involved in cell adhesion, cell–cell or cell–matrix interactions, as well as by promoting neuroinflammation." (PMID 37108212, 2023).
neurodegenerative disease (continued). "Therefore, exploring the clinical relevance of compounds that activate physiological AhR signaling may provide new therapeutic targets in neurodegenerative disease." (PMID 34685709, 2021). "Studying the underlying mechanisms of how HeLa cells trigger the synthesis of AHR in response to autophagy induction by nutrient deprivation might reveal a potential role of AHR in the autophagy-related diseases, such as neurodegenerative diseases and tumorigenesis." (PMID 32414129, 2020). "As an endogenous metabolite of astrocyte KP, KYNA exerts anti-inflammatory and antioxidant functions by binding to aryl hydrocarbon receptor (AHR) and is widely used in treating neurodegenerative diseases." (PMID 38673879, 2024). "Because of the evidence of the neuroprotective effects of AhR against neurodegenerative diseases of the brain, research on non-toxic AhR agonists will be necessary and may help to alleviate the symptoms as a new therapeutic strategy against these diseases." (PMID 35743162, 2022).
neurological disorders (14 papers, 2014 to 2026). "This interaction between the microbiome and AhR is crucial in the gut–brain axis, where disruptions in AhR signaling have been linked to various neurological disorders." (PMID 39859522, 2025). "IAA, other than being implicated in neurological disorders, has widely been studied for its role as aryl hydrocarbon receptor (AhR) in regulation of intestinal immunity." (PMID 31920519, 2019). "Dysregulation of AhR is associated with aging and neurological disease." (PMID 34522212, 2021). "Results also demonstrated that proinflammatory molecules such as S100B, IL-17, IL-33, and neurological disease signaling pathways were upregulated, while protective pathways like aryl hydrocarbon receptor signaling were downregulated." (PMID 38719902, 2024). "The inactivation or overactivation of the AHR pathway has been demonstrated to contribute to the dysregulation of proinflammatory and neurodegenerative mechanisms in several neurological diseases." (PMID 38672460, 2024). "Both systemic and brain inflammatory conditions stimulate this pathway, including cytokine-induced IDO activation, thus contributing to kynurenine/AHR activation in several neurological disorders." (PMID 31606043, 2019). "Molecular biological studies have reported that TCDD may increase the risks of these neurological diseases by accelerating brain aging and inducing atypical neurodevelopment, partly mediated by the aryl hydrocarbon receptor." (PMID 42198545, 2026). "Specifically, AhR mRNA is enriched in the dentate gyrus granule cells of the adult hippocampus, a crucial structure for high-cognition tasks, such as episodic learning, spatial learning, and memory, which are often disrupted in neurologic disorders." (PMID 30225360, 2018). "AhR is also present in neural cells and can be involved in the mechanisms leading to PAH-induced neurological disorders." (PMID 36703634, 2022).
adenocarcinoma (13 papers, 2017 to 2025). A common cancer characterized by the presence of malignant glandular cells. "We sought to determine the effect of AhR deficiency on adenocarcinoma formation in the intestines of AOM/DSS mice." (PMID 37781044, 2023). "Interestingly, the proliferation of adenocarcinoma cells of AOM/DSS mice was inhibited by AhR deficiency." (PMID 37781044, 2023). "The obtained results indicate that adenocarcinoma of CRC has a slightly elevated expression of the AHR in all clinical stages." (PMID 41465541, 2025). "High AhR expression has also been reported from adenocarcinoma cell lines and in human ADC biopsies AhR immunostaining was higher than in normal bronchial tissue and SCC." (PMID 37696458, 2023). "Our study aimed to assess transcriptional activity of genes associated with the biotransformation of xenobiotics and endobiotics in all three phases in the CRC adenocarcinoma, including correlations between them, as well as the aromatic hydrocarbon receptor (AhR) pathways." (PMID 41465541, 2025). "Furthermore, AhR is reported to be abundantly expressed in solid lung tumours, especially in adenocarcinomas." (PMID 35101137, 2022). "Furthermore, histological analysis of colon revealed that A. muciniphila did not increase the malignancy of adenocarcinoma in the AhR-deficient ApcMin/+ mouse model, compared to that in the ApcMin/+ mouse model." (PMID 37781044, 2023).
intestinal diseases (13 papers, 2018 to 2025). "Our study reveals new insights into the association between AHR expression in EGCs and key pathological features of intestinal disorders, including inflammation, barrier dysfunction, and visceral hypersensitivity." (PMID 40225339, 2025). "Our results underscore the importance of gene–diet interactions in maintaining gut health and highlight AHR as a potential therapeutic target for dietary modulation strategies aimed at preventing or mitigating intestinal disorders." (PMID 40867804, 2025). "We next used LPS‐treated Caco‐2 cells acting as in vitro model with intestinal disorder to further explore the roles of AhR and Wnt/β‐catenin signaling pathway in epithelial cells." (PMID 39041942, 2024). "Most recently, the targeting of the aryl hydrocarbon receptor (AhR) with gut microbiota phenolic metabolites has been recognized as a crucial mechanism in the prevention and treatment of intestinal diseases." (PMID 37627637, 2023). "Moderation is necessary to maintain homeostasis, and if the AHR activation level is lower or higher than optimal, intestinal disorders appear." (PMID 37179416, 2023). "Excessive AHR activation can result in intestinal immune dysregulation and even intestinal diseases." (PMID 37179416, 2023). "Activation of AHR has beneficial effects on intestinal immune responses, but inactivation or overactivation of AHR can lead to intestinal immune dysregulation and even intestinal diseases." (PMID 37179416, 2023). "A number of studies have shown that AHR and AHR agonists maintain gut health and protect against intestinal diseases." (PMID 35923391, 2022). "In addition, a growing body of research has demonstrated that TCM has great potential in treating intestinal diseases by regulating intestinal immunity and inflammation through the AHR pathway." (PMID 37179416, 2023). "In DSS-inducible intestinal injury models, AhR-null mice exhibit severe symptoms and mortality, and in another study of intestinal disease models, 2,3,7,8-tetrachlorodibenzo-p-dioxin (TCDD)-induced AhR activation decreased lethality and symptom severity." (PMID 29468141, 2018). "Therefore, identification of specific gut microbes, including L. reuteri strains, that activate AhR independent of tryptophan metabolism is important for developing AhR-mediated biotherapeutic strategies to target intestinal diseases." (PMID 30389766, 2019).
lung (11 papers, 2010 to 2025). "A recent study suggests that anaerobic Peptostreptococcus anaerobius fosters colorectal carcinogenesis by producing the tryptophan metabolite, trans-3-indoleacrylic acid (IDA), which inhibits ferroptosis through activating the aryl hydrocarbon receptor (AHR)." (PMID 38844964, 2024).
respiratory diseases (9 papers, 2014 to 2026). "We highlight research suggesting and elucidating how PAHs and AhR-dependent mechanisms might be linked to cellular processes central in development and exacerbation of respiratory diseases." (PMID 33187512, 2020). "Thus, several literature searches were performed in PubMed using various combinations of PAHs, specific PAHs or AhR and terms linked to respiratory diseases, including inflammatory responses, immune system, autonomic nervous system, lung development, lung infection, asthma and COPDs." (PMID 33187512, 2020). "Some studies have also confirmed that AhR regulates the immune response of various respiratory diseases and shown that the lung is sensitive to ligands using the gene-deficient mice that were given the agonists and antagonists." (PMID 37256962, 2023). "Aryl hydrocarbon receptor (AHR) genomic pathway has been well-characterized in a number of respiratory diseases." (PMID 34576152, 2021). "The lung is sensitive to AhR ligands, and AhR modulates the immune response in various respiratory diseases." (PMID 29670460, 2018). "Furthermore, our work highlights the potential of EVs as sensitive indicators of AhR activity and offers new insight into therapeutic strategies targeting AhR signaling in respiratory disease." (PMID 41882680, 2026). "Thus, the 3-IAld/AhR axis could be therapeutically exploited for tissue immune homeostasis, microbial symbiosis, and pathogen resistance in CF and other respiratory diseases." (PMID 29670460, 2018). "AhR serves as a key sensor and effector molecule for environmental pollutants such as PM2.5, playing a significant role in the development and progression of inflammatory and respiratory diseases through the mediation of oxidative stress, inflammatory responses, and immune regulation." (PMID 40559961, 2025).
infectious disease (8 papers, 2012 to 2026). A disorder directly resulting from the presence and activity of a microbial, viral, or parasitic agent in humans. "Collectively, field and laboratory data provide strong evidence that fish populations exposed to AhR-activating xenobiotics are particularly at risk to infectious diseases." (PMID 34502366, 2021). "Importantly, we showed that local treatment with a non-toxic, non-persistent, physiological AhR ligand had beneficial effects on experimental leishmaniasis in susceptible mice, opening possibilities of further studies on the effects of AhR-signaling in infectious diseases like leishmaniasis." (PMID 31749794, 2019).
psychiatric disorder (7 papers, 2019 to 2025). A disorder characterized by behavioral and/or psychological abnormalities, often accompanied by physical symptoms. "Importantly, microbial-derived metabolites modulate the intestinal immune response via the activation of aryl hydrocarbon receptor (AHR) to promote resilience to stress-induced psychiatric disorders by evoking adaptive changes." (PMID 38671931, 2024).
hematological malignancies (6 papers, 2012 to 2024). "The physiological effects of AhR activation play a key role in carcinogenesis and immune modulation, as AhR is highly expressed and chronically activated in both hematological malignancies and solid tumors." (PMID 34290693, 2021). "Although our understanding of the physiological roles of the AHR in the immune system is evolving, there is little known about its role in hematopoiesis and hematopoietic diseases." (PMID 30388136, 2018). "The AHR signaling pathway plays an important role in hematologic malignancies." (PMID 39125717, 2024). "While the normal, physiological role of AHR is not fully understood, it regulates aspects of HSC function, immune system development, and hematopoietic diseases." (PMID 30388136, 2018). "Previous research has shown that AHR and HIF-1α are important in hematological malignancies." (PMID 34572746, 2021).
neurodevelopmental disorder (6 papers, 2021 to 2025). A behavioral and cognitive disorder with onset during the developmental period that involves impaired or aberrant development of intellectual, motor, or social functions. "In conclusion, these findings indicate PFOSA causes neurodevelopmental disorders by inducing oxidative stress and apoptosis through the AhR pathway." (PMID 41150530, 2025). "Therefore, the interplay between AHR and the androgen receptor (AR), which is linked to dysfunction of the serotonergic system, could contribute to the onset of neurodevelopmental disorders such as ASD." (PMID 39812050, 2025). "Our findings underscore Faecalibacterium-mediated AhR modulation as a promising therapeutic strategy for ASD, highlighting the dual potential of Faecalibacterium-based probiotics and targeted interventions against indole-AhR signaling to address neurodevelopmental disorders." (PMID 40919211, 2025). "In summary, the modulation of the AHR signalling pathway by tryptamine is pivotal for various physiological processes and may contribute to the development of neurodevelopmental disorders such as ASD and the progression of neurodegenerative diseases such as AD, Huntington's disease, and PD." (PMID 39812050, 2025). "Taken together, and compared to other PCDD congeners, TCDD might have more specific AhR-dependent toxicity to induce mitochondrial dysfunction, which is involved in the pathophysiology of neurodevelopmental disorders, such as ASD and ADHD, observed in children from the Da Nang cohort." (PMID 36850978, 2023).
bone disorder (5 papers, 2020 to 2024). "The mechanisms through which the AhR and Hes1 are regulated must be explored further to better understand CKD-related bone disorders." (PMID 39201457, 2024).
brain diseases (5 papers, 2021 to 2025). "Because loss of AhR seems to predispose both peripheral and central immune cells to heightened immunological responses, targeting AhR may be an intriguing therapeutic strategy to mitigate neuroinflammatory processes in various brain diseases." (PMID 41324080, 2025). "This study elucidated an anti-inflammatory mechanism for curcumin in astrocytes that required AhR mediation and a more detailed understanding of the mechanism of curcumin in terms of its therapeutic effects on neuroinflammation resulting from brain diseases." (PMID 35458704, 2022). "This review provides an overview of the impact of AhR pathways on various aging hallmarks in the brain and the implications for AhR signaling as a mechanism in regulating aging-related diseases of the brain." (PMID 34685709, 2021). "Below is an overview of the effects of AhR signaling in prominent aging-related brain diseases." (PMID 34685709, 2021). "Specifically, we will focus our attention on some trp metabolites with specific neuroactive features, whose imbalance or deficiency could be involved in the pathophysiology of aging-related brain diseases in the context of AHR signaling pathways and regulatory functions." (PMID 39175504, 2024). "In addition, the well-known AhR signaling of tryptophan metabolites constituting the interface of microbiota–gut–brain axes, could suppress pro-inflammatory cytokines in astrocytes and microglia, and has the potential to participate in several brain diseases including AD." (PMID 33466861, 2021).
heart disease (5 papers, 2012 to 2026). "We find that abnormalities induced by AHR disruption in utero persist long after removal of the inducing agent and have a significant effect on predisposing the adult to cardiac disease." (PMID 26555816, 2015). "Increasing evidences to date have pointed to an importance for AhR in controlling the extent of inflammatory reactions in response to heart diseases in animal models, and it would be interesting to test whether AhR was also affected by baicalin in clinical settings." (PMID 29935544, 2018).
GI tumor (4 papers, 2024 to 2025). "Broccoli is a rich source of AHR in the gut of mice that are sensitive to specific environmental toxicants and develop mucosal disorders and GI tumors, Ahrb/b, or the less sensitive, Ahrd/d mice." (PMID 38779039, 2024).
endocrine disorders (3 papers, 2019 to 2024). "In boars, the combination of AHR and TCDD can cause endocrine disorders, reduced sperm, altered sexual behavior and reduced fertility." (PMID 31861561, 2019).
retinopathy (3 papers, 2014 to 2022). "Using an animal model of retinopathy—OXYS rats—in the present work, we explored the influence of SkQ1 on mRNA expression of AhR, Nrf2, and their dependent genes; those genes can regulate oxidative and antioxidant processes in the cells." (PMID 25132985, 2014).
gastro-intestinal disease (2 papers, 2020). "Trp metabolism and AhR signaling have been implicated in several neurological, metabolic and gastrointestinal diseases." (PMID 32957545, 2020).